PTH (parathyroid hormone)
Diseases named in the same sentence as PTH in open-access papers (continued):
Sharing a sentence is not in itself a finding about the gene and the disease.
parathyroid carcinoma (continued). "Of note, a similar review from 2020 identified 12 published cases of parathyroid carcinomas in children, in addition to a new report of a 13-year-old male (with a baseline total serum calcium of 15.43 mg/dL and PTH of 980 pg/mL)." (PMID 37893182, 2023). "In patients with parathyroid carcinoma, serum calcium levels are typically higher than those with benign primary hyperparathyroidism, and PTH levels are elevated by 3–4 times." (PMID 40729208, 2023). "The majority of parathyroid cancers (90%) are hormonally functional tumors, with clinical manifestations of hypercalcemia as a result of excessive PTH serum levels." (PMID 36984449, 2023). "Previous studies have shown that parathyroid carcinoma occurs with equal frequency in both sexes and usually increases serum PTH to five- to tenfold of the normal upper limit." (PMID 35414046, 2022). "Owing to the PTH value, size of the tumor, and adhesion to adjacent tissues, the patient was diagnosed with parathyroid carcinoma, and the tumor, right lobe of the thyroid, and adjacent lymph nodes were resected." (PMID 35414046, 2022). "Non-PTHrP pathways consist of osteolytic metastasis, overproduction of 1,25 vitamin D, and parathyroid carcinoma and ectopic production of PTH." (PMID 35187010, 2022). "High calcium, high PTH, parathyroid occupation by ultrasound, and intraoperative invasion should be considered to have the possibility of parathyroid cancer." (PMID 36193301, 2022). "When serum calcium exceeds 12 mg/dL (3 mmol/L), serum PTH levels exceed the normal upper limit by 3–10 times, and awareness of the possibility of parathyroid carcinoma is necessary." (PMID 34420520, 2021). "Postoperative pathology showed one case (case 4) of parathyroid carcinoma with a serum calcium level of 4.21 mmol/L and serum PTH level of 2603.6 pg/ml." (PMID 34420520, 2021). "On presentation, the patient with parathyroid carcinoma had a calcium level of 15 mg/dL and PTH was 2237 pg/mL and it took nine days for his calcium to get normalized during the hospital stay." (PMID 34322336, 2021). "As the newest generation of calcimimetic, cinacalcet was proven to be effective in patients with inoperable parathyroid cancer by increasing the affinity of calcium-sensing receptors and reducing the secretion of parathyroid hormone." (PMID 35154009, 2021). "Oncological follow-up of the three patients treated for parathyroid carcinoma showed cure of cancer in two of them, while the third had lung metastasis with controlled PTH and calcium levels." (PMID 33382714, 2020). "The most suspicious features of parathyroid carcinoma are PTH at least 10 times higher than normal, serum calcium higher than 3.5 mmol/L, parathyroid lesion measuring more than 3 cm in its highest dimension, and concomitant severe kidney and bone diseases." (PMID 32884778, 2020). "The mechanism of action of cinacalcet is the decrease in PTH production, which makes it an apt choice for parathyroid cancer related hypercalcemia." (PMID 31661917, 2019). "99mTc-MIBI SPECT/CT is valuable for localizing the primary lesion, while serum PTH serves as a robust biomarker of presurgical parathyroid carcinoma and an excellent indicator of recurrence and metastasis." (PMID 30290620, 2018). "In view of the phenomenally high levels of parathyroid hormone, (more than 10 times upper limit of normal), the pre-operative suspicion of parathyroid cancer was high." (PMID 30157930, 2018). "In our case, the PTx allowed us to both treat the ectopic calcification and diagnose it as parathyroid carcinoma, and the serum calcium and PTH dropped when parathyroid carcinoma was removed." (PMID 29047366, 2017). "Cinacalcet can also suppress PTH secretion due to parathyroid carcinoma in the same way as it does for parathyroid hyperplasia in the uremic condition." (PMID 29047366, 2017).
parathyroid carcinoma (continued). "Calcimimetics are orally active agonists of the CaSR, used for treating PTH hypersecretion in end stage kidney disease and parathyroid carcinoma by enhancing receptor sensitivity to extracellular calcium and inhibiting PTH secretion." (PMID 25695075, 2015). "Several preoperative factors can predict parathyroid carcinoma such as tumor size larger than 3 cm, alkaline phosphatase more than 285 IU/L, younger age, hard consistency, high serum calcium, and PTH levels." (PMID 25177504, 2014). "Pathology from en bloc resection was parathyroid carcinoma and immunohistochemical study revealed positivity for PTH." (PMID 25177504, 2014). "After surgery, the patient’s calcium and parathyroid hormone levels normalized, but histology confirmed parathyroid carcinoma with capsular and vascular invasion." (PMID 23566353, 2013). "We presented a rare case of parathyroid crisis secondary to giant parathyroid cystic adenoma extending into the mediastinum, with very high serum calcium and Intact PTH levels, mimicking a parathyroid carcinoma." (PMID 22840059, 2012). "Case series studying solitary parathyroid adenomas with asymptomatic disease derived mean preoperative PTH levels of 186 pg/mL and 165 pg/mL, while research studying parathyroid carcinoma yielded higher PTH levels of 714 pg/mL and 1220 pg/mL." (PMID 22840059, 2012). "In view of the marked elevations of serum calcium and PTH that are common in parathyroid crisis, parathyroid cancer should be considered in any differential diagnosis of this condition." (PMID 19016595, 2008). "In the presented case, there was a high index of suspicion for parathyroid carcinoma given the severity of the clinical presentation, which included hypercalcemic crisis with psychosis and muscle weakness, alongside markedly elevated calcium and PTH levels." (PMID 41568161, 2026). "Studies states that preoperative diagnosis of parathyroid carcinoma is difficult before surgery but different clinical clues can be helpful like early age of presentation, markedly elevation of serum parathyroid hormone and a serum calcium of more than 14 mg/dl." (PMID 41181504, 2025). "The case report outlines a 33-year-old woman with neurofibromatosis type 1 (NF1) presenting complex symptomatology including a cervical mass, bone pain and significantly elevated calcium and parathyroid hormone levels, indicative of parathyroid carcinoma accompanied by cystic fibrous osteitis." (PMID 39932063, 2025). "Laboratory values of PTH and serum calcium cannot differentiate between various causes of PHPT, unless serum calcium is more than 14 mg/dL or PTH is more than three times the upper limit of normal, in which case parathyroid carcinoma should be suspected." (PMID 39061231, 2024). "Often, markedly elevated PTH levels are observed in parathyroid carcinoma patients." (PMID 39529981, 2024). "In addition to benign primary hyperparathyroidism, an elevated PTH value is present in parathyroid carcinoma and in rare cases of ectopic PTH secretion by tumors." (PMID 37265703, 2023). "The patient with parathyroid cancer had the highest levels of calcium and PTH." (PMID 36107253, 2023). "The catabolic action of PTH in parathyroid carcinoma brings consistent mineral bone density reduction, leading to osteitis fibrosa cystica, characterized by several manifestations, such as bone cysts, brown tumors, and increased incidence of fragility fracture." (PMID 35872978, 2022). "Indeed, we were unable to surgically control the high levels of PTH originating from metastatic ectopic foci of the parathyroid carcinoma in the lung parenchyma, mediastinal lymph nodes and bone." (PMID 35676731, 2022). "The PTH decrease suggests effective removal of the parathyroid carcinoma." (PMID 32149123, 2020).
parathyroid carcinoma (continued). "Failure of PTH to decrease significantly after surgery could exclude ectopic parathyroid adenoma, and metastasis secondary to parathyroid carcinoma should thus be suspected, with MRI representing a valuable tool for further diagnosis." (PMID 30290620, 2018). "Serum PTH and CgA serve as circulating biomarkers in parathyroid carcinoma, and raised levels of PTH and CgA together with locoregional lymphadenopathy may indicate parathyroid carcinoma." (PMID 30290620, 2018). "Hence, parathyroid carcinoma should be borne in mind while dealing with huge, palpable parathyroid masses, with very high serum calcium and PTH levels." (PMID 22840059, 2012). "Similarly the PTH level in parathyroid carcinoma is consistently higher than for benign parathyroid disease." (PMID 23050135, 2012). "The significant reduction in postoperative PTH levels in 77% of patients highlights the efficacy of surgical intervention, especially when concomitant or en bloc resection of PC and the thyroid is performed (84% in our cohort), which remains the cornerstone of treatment for parathyroid carcinoma." (PMID 40142758, 2025). "Generally, parathyroid carcinoma is more frequently characterized by renal involvement (56-84% accompanied by nephrolithiasis), high serum calcium levels (>3.5mmol/L), and a significant increase in PTH concentration (exceeding 10 times the upper limit of the reference value)." (PMID 39020280, 2024). "However, they have considered that patients who present with a palpable mass, a serum total calcium level higher than 3.5 mmol/L, markedly elevated PTH levels, severe renal and/or bone disease and/or laryngeal nerve palsy should be suspected of harboring a parathyroid carcinoma." (PMID 32884778, 2020). "Other clinical and imaging features, such as high plasma levels of calcium and parathyroid hormone (PTH) and tumor size, also favor the possibility of parathyroid carcinoma preoperatively." (PMID 32884778, 2020). "Parathyroid carcinoma was also kept in suspicion but it was ruled out post-report of histopathology came and with normalization of the calcium and parathyroid hormone levels post-surgery." (PMID 41181504, 2025). "Diagnosing primary non-functional parathyroid carcinoma can be especially challenging in cases with negative PTH immunohistochemistry." (PMID 40762649, 2025). "Intraoperative assessment was made on the appearance, adherence and invasiveness of gland to surrounding structures to rule out parathyroid carcinoma with monitoring of intraoperative PTH level." (PMID 41181504, 2025). "Parathyroid carcinoma is not very common and is difficult to diagnose preoperatively, but if the patient is of young age with very high levels of PTH and calcific foci are seen in the parathyroid, then parathyroid carcinoma can be suspected." (PMID 40612282, 2025). "While the third patient with parathyroid carcinoma did not demonstrate elevated serum hCG levels, the patient demonstrated drastically lower levels of PTH, raising the possibility of a non-secretory lesion." (PMID 40530390, 2025). "The PTH protein of hESC‐PT/IPSC‐PT cells existed in cytoplasm and nucleus, which was similar to the immunofluorescence staining results of poorly differentiated parathyroid carcinoma cells." (PMID 38494923, 2024). "High levels of PTH usually indicate PHPT or, less frequently, parathyroid cancer." (PMID 38920679, 2024). "There is no agreed interval or threshold for PTH and serum calcium levels to define parathyroid cancer." (PMID 36984449, 2023). "Immunotherapy against parathyroid hormone in advanced and refractory parathyroid carcinomas has shown tumor regression with hormonal and biochemical normalization." (PMID 35326576, 2022). "There were no osteolytic metastatic lesions on PET-CT and bone scans in this patient, nor did he exhibit elevated 25-OH vitamin D or parathyroid carcinoma with ectopic production of PTH." (PMID 35187010, 2022).
parathyroid carcinoma (continued). "The serum PTH, Ca, and ALP levels of 4 cases of parathyroid carcinoma." (PMID 30290620, 2018). "This is a report of non-functioning parathyroid carcinoma diagnosed by reverse transcription polymerase chain reaction (RT-PCR) targeting parathyroid hormone (PTH) messenger RNA." (PMID 28726134, 2017). "This is the first report of non-functioning parathyroid carcinoma diagnosed by reverse transcription polymerase chain reaction (RT-PCR) targeting PTH messenger RNA (mRNA)." (PMID 28726134, 2017). "Although the tumor cells were slightly positive for PTH, the diagnosis of non-functioning parathyroid carcinoma was finally made by detecting PTH by RT-PCR, which offers increased sensitivity compared with immunohistochemical staining." (PMID 28726134, 2017). "Elevated serum PTH and calcium levels are present in persistent or recurrent disease in greater than half of patients with parathyroid carcinoma who are not cured by their initial treatment." (PMID 16504029, 2006). "Parathyroid carcinomas may be suspected with serum calcium > 14–15 mg/dL and markedly elevated levels of PTH; however, <10% of parathyroid carcinomas can be hormonally non-functional and can only be suspected based on clinical examination findings." (PMID 39061231, 2024). "As demonstrated in our patient, the presence of a palpable neck mass, nephrocalcinosis, and markedly elevated parathyroid hormone levels, far exceeding the upper limits of normal, suggested a diagnosis of parathyroid carcinoma rather than the more common benign parathyroid adenoma." (PMID 39822449, 2024). "In conclusion, parathyroid carcinoma is an extremely rare tumour in the setting of THP, and his clinical diagnosis could be difficult due to the presence of chronic kidney failure, which leads to an increase in PTH blood level." (PMID 33343947, 2020). "We diagnosed this tumor as non-functioning parathyroid carcinoma using RT-PCR for PTH mRNA." (PMID 28726134, 2017). "Non-functional parathyroid carcinoma (NFPC) is a particularly challenging diagnosis, especially in cases lacking PTH expression by immunohistochemistry." (PMID 40762649, 2025). "The serum calcium levels, serum PTH levels in the APT+PC group were higher than those with benign lesions, but there was some overlap; and the clinical data showed no specificity in the differentiation of benign and malignant parathyroid tumors." (PMID 40444080, 2025).
nephrolithiasis (90 papers, 2009 to 2026). The presence of a calculus in the pelvis of the kidney; this is most often composed of mineral salts and proteins. "High parathyroid hormone levels can lead to increased blood calcium levels, thereby increasing the risk of kidney stones." (PMID 40403294, 2025). "Previous studies have similarly emphasized that bone loss and nephrolithiasis in PHPT are primarily associated with the direct effects of parathyroid hormone (PTH) and local mechanisms." (PMID 40731865, 2025). "Parathyroid hormone and analogs, as well as Antiviral drugs, were found to be more likely to cause kidney stones compared to Antirheumatics." (PMID 39764463, 2024). "Its classic symptomatic form is characterized by elevated serum PTH and calcium levels associated with skeletal and renal complications such as osteoporosis and fractures, chronic renal failure, nephrolithiasis, and/or nephrocalcinosis." (PMID 39404961, 2024). "Among the top 30 drugs, we found that the most common drug classes associated with the occurrence of kidney stones are Antirheumatics, Antiviral drugs, parathyroid hormone and analogs, and Immunosuppressants." (PMID 39764463, 2024). "Secondarily, similarly to the general population, hypomagnesaemia increased the risk of kidney stones in patients with PTH-related ailments too." (PMID 39051301, 2024). "In 2015, a GWAS in Icelanders reported that common variants of rs12654812 was associated with nephrolithiasis, and rs12654812 associated significantly with decreased serum PTH levels and serum phosphate." (PMID 35910217, 2022). "D)—parathyroid hormone (PTH) axis, which not only leads to kidney stone formation but is also associated with increased carotid IMT." (PMID 32182704, 2020). "The A allele of CASR rs7652589 was recognized in our study as a risk allele for severe nephrolithiasis, among other possible factors, such as gender, age, serum concentrations of Ca and PTH, and the G allele of CCL2 rs1024611." (PMID 27739473, 2016). "In a cohort of patients with kidney stones, high normal serum Ca and low normal PTH concentrations, nine known sequence variants of the CYP24A1 gene were detected." (PMID 26332888, 2015). "The reduction in serum PTH levels associated with the kidney stone variants likely results from a decrease in serum phosphate levels caused by diminished renal reabsorption as a consequence of the negative feedback loop that maintains serum phosphate levels." (PMID 26272126, 2015). "Five of the cases did not describe symptoms, one case mentioned an asymptomatic patient with normal PTH levels and elevated calcium, one patient developed pancreatitis, and other patients developed nephrolithiasis, bone loss and fractures, fatigue, and muscle cramps." (PMID 28003924, 2016). "PTH also causes renal damage and renal calculi, after which HT may develop." (PMID 29176783, 2017). "More severe Hypop and higher calcium and PTH levels are expected in PHPT patients with kidney stones." (PMID 41509939, 2025). "We evaluated the albumin-corrected calcemia, calciuria, PTH, 25(OH)D level, serum phosphate, bone mineral density, and major clinical symptoms (fracture, nephrolithiasis)." (PMID 39040613, 2024). "NC-PHPT, which is often discovered during evaluation for nephrolithiasis or suspected metabolic bone disease, is characterized by elevated PTH values together with normal serum calcium levels." (PMID 39404961, 2024). "In that study, cinacalcet at doses that normalized PTH levels reduced the number and diameter of kidney stones after 10 months." (PMID 39055046, 2024). "D)—parathyroid hormone (PTH) axis, which has been proven to be associated with higher risk of symptomatic kidney stones." (PMID 36637005, 2023). "To address these gaps in care, we plan to implement emergency room order sets that include parathyroid hormone testing for patients with kidney stones and to establish a reflex lab protocol for triggering a comprehensive workup for PHPT." (PMID 38143641, 2023).